CXCL16 (C-X-C motif chemokine ligand 16)
Diseases named in the same sentence as CXCL16 in open-access papers (continued):
Sharing a sentence is not in itself a finding about the gene and the disease.
atherosclerosis (continued). "CXCL16 has been demonstrated to be involved in the development of atherosclerosis and myocardial infarction (MI)." (PMID 28286356, 2017). "Further, elevated serum levels of CXCL16 were found in patients with renal injury, acute coronary syndrome, atherosclerosis, or cardiac surgery." (PMID 28267793, 2017). "The major pathological feature of atherosclerosis is the formation of foam cells, derived from either macrophages or smooth muscle cells, and CXCL16 is expressed on the surface of macrophages, arterial smooth muscle cells and vascular endothelial cells." (PMID 24460887, 2014). "Previous studies have linked CXCL16 and its receptor CXCR6 to inflammation-associated cancers, renal fibrosis, and vascular inflammatory diseases, such as atherosclerosis." (PMID 22748184, 2012). "Accumulating evidences have shown that CXCL16 is a marker of inflammation, atherosclerosis and acute coronary syndrome in humans." (PMID 23056624, 2012). "CXCL16 is a biomarker of inflammatory bowel disease and diseases such as sarcoidosis and atherosclerosis." (PMID 21599948, 2011). "C-X-C motif chemokine ligand 16 (CXCL16) may serve a pro-inflammatory function in human atherosclerosis, particularly in acute coronary syndrome." (PMID 35865542, 2022). "CXCL16 can scavenge oxLDL, thus antagonizing atherosclerosis progression." (PMID 36555579, 2022). "Hence, CXCL16 as well as platelet CXCR6 act as potent peripheral blood mononuclear cell adhesion ligands to the atherosclerosis prone vessel wall and thus promote the progression of atherosclerosis." (PMID 33503867, 2021). "Previous studies of CXCL16 in cardiovascular disease mainly focus on atherosclerosis." (PMID 33637127, 2021). "With the characteristics including the chemoattractive, adhesive and scavenging features, CXCL16 plays a role in the atherosclerosis lesion formation, in which CXCL16 may acts as a pro-inflammatory factor." (PMID 34688276, 2021). "In addition, CXCL16 acts as an oxLDL clearance receptor to fight atherosclerosis, and the phagocytosis of oxLDL by macrophages in CXCL16-deficient mice was decreased." (PMID 35668739, 2021). "The soluble form of CXCL16 could promote inflammation and atherosclerosis via recruiting the inflammatory cells." (PMID 33637127, 2021). "CXCL16 plays an important role in the later stages of atherosclerosis." (PMID 33800554, 2021). "CXCL16 plays a significant role in atherosclerosis development and progression." (PMID 32676207, 2020). "However, there is still a need to demonstrate that anti-CXCL16 monoclonal antibody therapy has efficacy in an animal model of atherosclerosis." (PMID 33182772, 2020). "The expression of other atherogenic biomarkers such as Timp1, Mmp9, Cxcl16, and Klf5 was also similar between groups, as analyzed by real-time PCR, indicating a different mechanism operating in the MG-induced reduction of atherosclerosis development in Apoe−/− mice." (PMID 30959963, 2019). "In recent years, CXCL16 was found to participate in the development of atherosclerosis." (PMID 24460887, 2014). "Interestingly, IL-18-mediated increase of atherosclerosis is accompanied by elevation of SR-PSOX/CXCL16 expression." (PMID 21042583, 2010). "In addition, various immune-related genes have been examined in an atherosclerosis animal model, and genes such as CXCR6, CXCL10, CXCR3 and CXCL16/scavenger receptor have been shown to be involved in the progression of atherosclerosis in animal models." (PMID 18673543, 2008). "Therefore, CXCL16 participates in the pathological progression of atherosclerosis." (PMID 40165931, 2025).
atherosclerosis (continued). "In addition, psoriatic patients with diagnosed atherosclerosis by medical imaging (transabdominal ultrasound or computed axial tomography or thoracal X-ray) displayed higher amounts of CXCL16 on their peripheral blood monocytes than psoriatic patients without atherosclerosis." (PMID 35784287, 2022). "In the case of atherosclerosis, M1 macrophages recognize ox-LDL by means of scavenger receptors including scavenger receptor A, CD 36, and CXCL16." (PMID 33925858, 2021). "During the past two decades, the role of CXCL16 and its receptor CXCR6 in the development of myocardial diseases and atherosclerosis has been controversially discussed." (PMID 26499307, 2016). "Targeted disruption of CXCL16 and LDL receptor is shown to promote atherosclerosis." (PMID 38519881, 2024). "In line with this, psoriatic patients with coincident atherosclerosis expressed elevated levels of CXCL16 on monocytes compared with patients without vascular comorbidities." (PMID 35784287, 2022). "CXCL16 and CXCR6 were recently observed to be related to various inflammatory diseases, such as glomerulonephritis, pulmonary diseases, atherosclerosis, coronary artery disease, rheumatoid arthritis and many inflammation-related cancers." (PMID 34539750, 2021). "CXCL16 explicitly combines with Ox LDL, indicating that it probably relates to atherosclerosis." (PMID 34046056, 2021). "Current work on SR regulation of atherosclerosis focuses largely on five SR classes: SR-A; SR-B (CD36 (cluster of differentiation 36)); SR-E (lectin-like oxidized LDL receptor-1 (LOX-1)); SR-G (CXCL16); SR-J (receptor for advanced glycation end-products (RAGEs))." (PMID 33182772, 2020). "Membrane-bound CXC chemokine ligand 16 (CXCL16) has been reported as a scavenger receptor that internalizes oxidized LDL and might be involved in the progression of atherosclerosis." (PMID 30071823, 2018). "While in a soluble form, CXCL16 has been found to interact with its receptor, CXCR6, and thus functions as an attractant and adhesion molecule for CXCR6-expressing T cells, which contribute to the development of atherosclerosis." (PMID 28286356, 2017). "Chemokine (C-X-C motif) ligand 16 (CXCL16), a membrane-bound chemokine, acts as a ligand for C-X-C chemokine receptor type 6 (CXCR6) and contributes to the progression of many chronic inflammatory diseases, including fibrosis, nonalcoholic fatty liver disease, atherosclerosis, and cancer." (PMID 38172124, 2024). "The clearest difference between these two groups was found in the expression of CXCL16 on non-classical monocytes with a nearly twice elevated chemokine expression in patients with psoriasis and atherosclerosis (MFI CXCL16 no atherosclerosis: 20.6; MFI CXCL16 atherosclerosis: 37.2)." (PMID 35784287, 2022).
glioma (32 papers, 2009 to 2025). A benign or malignant brain and spinal cord tumor that arises from glial cells (astrocytes, oligodendrocytes, ependymal cells). "Compared to healthy brain tissue, researchers have detected higher levels of CXCL16 in GBM tissue with contributions from both glioma cells and tumor-associated microglia." (PMID 41157253, 2025). "Glioma cells release the C-X-C motif chemokine ligand 16 (CXCL16), which differentiates TAMs to the M2 variant by signaling through CXCR6." (PMID 41157253, 2025). "CXCL16 is generated by tumor cells and supports the anti-inflammatory/pro-tumor polarization of glioma-associated microglia/macrophages, as well as inhibiting microglia polarization toward an inflammatory phenotype in response to LPS and IFN stimulation, according to recent research." (PMID 35269652, 2022). "It was reported that CXCL16 released by glioma cells may drive the polarization of microglia macrophages, called glioma associated microglia (GAMs) toward the anti-inflammatory/pro-tumoral phenotype." (PMID 32456359, 2020). "The presence of CXCL16 derived from glioma cells was observed to promote tumor invasion and proliferation through a chemokine receptor that binds the soluble form of CXCL16, C-X-C chemokine receptor 6 (CXCR6)." (PMID 41157253, 2025). "Recent studies demonstrated that CXCL16 signaling is a target to modulate macrophage phenotype to restrain inflammation and limit glioma progression." (PMID 37397378, 2023). "CXCL16 is highly expressed in human gliomas compared to a normal brain, where it is mainly found in vascular endothelial cells." (PMID 35267626, 2022). "As a final point, CXCL16 was demonstrated to be considerably expressed by glial tumor and stroma cells, whereas CXCR6 was found in stem cell fenotype cells." (PMID 35269652, 2022). "Microglia from glioma-bearing CXCR6-ko mice had lower expression levels of anti-inflammatory genes, compared to glioma-bearing wt mice that suggested CXCL16/CXCR6 axis involvement in the anti-inflammatory programming of microglia." (PMID 36686729, 2022). "CXCL16 is highly expressed in human gliomas, and compared with the normal brain were restricted to brain vascular endothelial cells." (PMID 35269652, 2022). "An over-expression of CXCL16 was noted in glial tumor and stroma cells, while CXCR6 expression is more likely associated with glioma-stem cells." (PMID 35269652, 2022). "On the contrary, human glioma cells express CXCL16 chemokine abundantly, both on mRNA and protein level, which are further upregulated by TNFα and IFNγ." (PMID 34200145, 2021). "In activated astroglial and glioma cells, transmembrane CXCL16 is shed to a soluble form by proteolytic cleavage, involving the activity of cell-surface MMPs." (PMID 34200145, 2021). "CXCL16/CXCR6 signaling acted directly on promoting tumor cell growth, migration and invasion by promoting glioma‐associated microglia/macrophages modulation toward a pro‐tumor phenotype, being a critical target for glioma treatment." (PMID 34482648, 2021). "Chemokine (C-X-C motif) ligand 16 (CXCL16)/chemokine receptor 6 (CXCR6) signaling elicits anti-inflammatory effects in glioma by driving microglia polarization." (PMID 33918635, 2021). "It was reported that CXCL16 released by glioma can drive the polarization of microglia cells, called “glioma-associated microglia/macrophages” toward an anti-inflammatory/protumor phenotype." (PMID 34200145, 2021). "In their study, CXCL16, released by glioma cells, drove TAMs towards an anti-inflammatory and thus protumoral phenotype in vitro." (PMID 34203660, 2021). "CXCL16 is highly expressed in human gliomas, where both mRNA and protein are upregulated by TNFα and IFNγ." (PMID 32456359, 2020). "All these data confirm that CXCL16 released by glioma cells concurs to tumor progression, and promotes tumor cell proliferation." (PMID 30542347, 2018).
glioma (continued). "We also describe that CXCL16/CXCR6 signaling acts directly on mouse glioma cells, as well as human primary GBM cells, promoting tumor cell growth, migration and invasion." (PMID 30542347, 2018). "For the first time we demonstrated that CXCL16/CXCR6 axis plays a role in promoting glioma growth, directly acting on tumor cells." (PMID 30542347, 2018). "CXCL16 is expressed in human glioma, while the presence of CXCR6 is controversial, likely associated with glioma-stem cells." (PMID 30542347, 2018). "In previous investigations we and others determined that CXCL16 is definitely involved in tumor progression of different tumor types, e.g. gliomas, schwannomas, lung and breast tumors." (PMID 27784296, 2016). "Primary microglia cells were incubated for 24 h with glioma conditioned medium (GCM) in the presence of neutralizing anti-CXCL16 antibody (AbCXCL16) (GCM + AbCXCL16), or control IgG (GCM + IgG), and analyzed for the expression of pro- or anti-inflammatory genes." (PMID 30542347, 2018). "Thus, CXCL16 is the first chemokine released by glioma cells that has been proven to drive the interplay with GAMs to acquire a phenotype that supports tumor growth." (PMID 30542347, 2018). "All together these data suggest that CXCL16 signaling could represent a good target to modulate microglia phenotype in order to restrain inflammation or to limit glioma progression." (PMID 30542347, 2018). "Moreover, we show that CXCL16 produced by glioma cells directly stimulates the CXCR6 expressed by tumor cells, promoting their proliferation, migration and invasion." (PMID 30542347, 2018). "Facing the high CXCL16 expression levels in human meningiomas, we raised the question if “inverse signaling” of CXCL16 previously observed in highly malignant glioma cell might also take place in benign meningioma cells." (PMID 27784296, 2016). "CXCL16 is highly expressed by glial tumor and stroma cells in glioma." (PMID 27344170, 2016). "Thus, a reduction of GATA3 expression may be involved in CXCL16-regulated or CX3CL1-regulated inhibition of THSD4 expression in gliomas." (PMID 32346064, 2020). "In accordance with this effect, we also found that CXCL16 stimulation increased the expression level of the matrix metalloproteinases mmp9 and mmp2 (n = 6, p < 0.05; Student's t-test), whose activity is reported to be involved with the invasion ability of glioma cells." (PMID 30542347, 2018). "Additionally, in accordance with our recent findings in gliomas, application of a specific CXCL16 antibody (αCXCL16) which may also induce the intrinsic activity of tm-CXCL16, resulted in phosphorylation of both Akt and ERK1/2 (right side) after 20 min." (PMID 27784296, 2016). "Especially, CCR5/CCL5 and CXCR6/CXCL16 signaling modulates TAM polarization, as well as the proliferation and invasion of glioma cells." (PMID 37818357, 2023). "CXCL16/CXCR6 axis acts a pivotal part in the pro-tumor microenvironment, and the silencing of CXCR6 reduced the proliferation rate on glioma cells, indicating that CXCR6 plays an oncogenic role in glioma." (PMID 35571062, 2022). "Treatment of mouse glioblastoma microglia with both recombinant and glioma-released CXCL16 increased the expression of anti-inflammatory genes ARG1, CHIL3, RETNLA and CD163 that was impaired by anti-CXCL16 antibodies." (PMID 36686729, 2022). "In a mouse glioma model, brain tumor-infiltrating macrophages also expressed CD169 and produced the proinflammatory chemokines CXCL9, CXCL10, and CXCL16." (PMID 36266311, 2022). "TCGA database chemokine analysis showed that CXCL16 and CCL2 were significantly expressed in GBM tissue compared with WHO grade II and grade III glioma." (PMID 34638384, 2021). "While CXCL16 is widely expressed by glioma and glioma stromal cells in vitro and in situ, CXCR6 has been shown to likely be restricted to highly proliferative glioma stem cells." (PMID 34203660, 2021).
glioma (continued). "CXCL16/CXCR6 signaling acts directly on human primary GBM cells and mouse glioma cells, promoting tumor cell growth, invasion, and migration." (PMID 32456359, 2020). "The hypothesis that CXCL16 released from tumor cells acts in an autocrine/paracrine way to promote tumor progression is further confirmed by the significant reduction in tumor volume, proliferation, and infiltration in mice bearing glioma cells silenced for CXCL16." (PMID 30542347, 2018). "In line with what already reported, we found that CXCL16 is over-expressed in human GBM tissues obtained from patients and demonstrated, in vitro, that CXCL16 released by glioma cells acts as a mediator for microglia polarization." (PMID 30542347, 2018). "From our recent investigations, we know that CXCL16 is highly expressed in different human gliomas, while the corresponding receptor CXCR6 is restricted to a small subset of glioma cells with stem cell characteristics." (PMID 28698473, 2017). "In addition, CXCL16 as a chemokine as well as CXCR4 and CCR5 as chemokine receptors were identified in our study as possible vital immunomodulatory factors in glioma." (PMID 35896732, 2022). "In gliomas with high CASZ1 expression, we found a restricted infiltration level but upregulated chemokines, including CXCL16, CCL22, CCL25, and CXCL2, which could attract DCs and T cells." (PMID 36276925, 2022). "In the TCGA database, co-expression analysis of hub genes with chemokines and related receptors also showed a regular pattern, with CXCL16 as a chemokine as well as CXCR4 and CCR5 as receptors negatively correlated (all P < 0.05, r < − 0.3) with all hub genes in glioma." (PMID 35896732, 2022). "Given that, we hypothesized that NK CD56bright, Tfh, and macrophage cell types might be closely related to immune regulation in TME of glioma, and B7H3, PDCD1, LAG3 and CXCL16, CXCR4, CCR5 might be key targets for glioma immunotherapy." (PMID 35896732, 2022). "The original RNA-seq results suggested that glioma patients have higher levels of CCL20, CXCL1, CXCL2, CXCL5, and CXCL16 compared to noncancerous patients and that the levels of these small chemotactic cytokines in glioma are correlated with malignancy." (PMID 33483477, 2021). "Considering that CXCL16 specific receptor CXCR6 is diffusely expressed in the brain including in microglia cells, we wanted to investigate the role of CXCL16 in the modulation of microglia cell activity and phenotype, and in the progression of glioma." (PMID 30542347, 2018). "We initially demonstrated this mechanism in cultivated malignant human glioma cells, from which we had previously shown to express high levels of CXCL16, but a lack of the corresponding receptor CXCR6." (PMID 27784296, 2016). "Furthermore, stimulation with s-CXCL16 and s-CX3CL1 reduced caspase-3/7 activity that was induced by exposure to Temozolomide, a clinically used chemotherapeutic for gliomas." (PMID 26796342, 2016). "Inhibition of CXCL16/CXCR6 is not yet tested in clinical trials for glioma." (PMID 35267626, 2022). "Indeed, a single study previously examining the CXCL16/CXCR6 axis in GBM demonstrated that CXL16 expression in myeloid cells (particularly microglia) allows cells to adopt an anti-inflammatory state and that in the context of glioma, it contributes to immunosuppression." (PMID 38299146, 2023). "The absence of CXCR6 on glioma cells, but not on other cells of tumor microenvironment, reduces but does not block tumor development, suggesting that other signals are important for tumor progression, and again confirming that CXCL16/CXCR6 signaling acts also on cells of the tumor microenvironment." (PMID 30542347, 2018). "The results showed that there were trends linking these cytokines, CCL20, CXCL1, CXCL2, CXCL5, and CXCL16, to ADO expression in gliomas but these correlations were not significant, probably due to the low number of patients recruited to the study." (PMID 33483477, 2021).
glioma (continued). "A viral encoded putative receptor for CX3CL1, US28, was detected neither in glioma cells, nor in LOX melanoma cells, and thus, can be excluded for s-CXCL16 or s-CX3CL1 signaling." (PMID 26796342, 2016). "Both chemokines, s-CXCL16 and s-CX3CL1, significantly enhanced proliferation of classical receptor-negative, tm-chemokine-positive cells like U343 or A764 glioma cells, whereas double-negative cells like LOX melanoma cells did not respond." (PMID 26796342, 2016). "The validation outcomes of CXCL16, CXCR4 and CCR5 in the CGGA database exhibited consistent negative correlation trends, suggesting that CXCL16, CXCR4 and CCR5 might act as potentially vital chemokine elements in glioma." (PMID 35896732, 2022). "However, the representative chemokines in glioma (CXCL12, CXCL16, CX3CL1, CCL2) were not significantly correlated with poor OS in the same database." (PMID 34638384, 2021).